TRAF6 (TNF receptor associated factor 6)
Diseases named in the same sentence as TRAF6 in open-access papers (continued):
Sharing a sentence is not in itself a finding about the gene and the disease.
esophageal squamous cell carcinoma (4 papers, 2016 to 2023). Esophageal squamous cell carcinoma (ESCC) is a type of esophageal carcinoma (EC) that can affect any part of the esophagus, but is usually located in the upper or middle third. "The overexpression of TRAF6 oncoprotein has been reported to be associated with increasing tumorigenicity and metastasis of esophageal squamous cell carcinoma in vivo." (PMID 29703234, 2018). "Several studies demonstrated that TRAF6 was abnormally expressed and activated in tumor tissue, such as esophageal squamous cell carcinoma (ESCC), colon cancer, and pancreatic cancer." (PMID 34409101, 2021). "As for the role that TRAF6 played in cancer invasion and metastasis, a study on esophageal squamous cell carcinoma revealed that TRAF6 promoted migration and metastasis by regulating the RAS pathway." (PMID 27708550, 2016). "Although there was no in vitro experiment on the metastasis in this study, based on existing literatures, HCC may be similar with esophageal squamous cell carcinoma where TRAF6 influences cell migration and metastasis, which we will perform experiments to verify." (PMID 27708550, 2016).
Hepatic steatosis (4 papers, 2018 to 2025). Steatosis is a term used to denote lipid accumulation within hepatocytes. "Interestingly, TRAF6 ubiquitination has been shown to be increased in HFD-fed mice and to be associated with fatty liver, while its inhibition was recently shown to alleviate hepatic steatosis and liver fibrosis." (PMID 37140993, 2023). "TRAF6 can activate TAK1 by boosting TAK1’s ubiquitination, which exacerbates hepatic steatosis and inflammation." (PMID 40292292, 2025).
Hyperglycemia (4 papers, 2021 to 2025). An increased concentration of glucose in the blood. "Research on DPN in mice has shown that hyperglycemia causes downregulation of miR-146a expression, which is inversely related to inflammatory IRAK1 and TRAF6 protein levels in dorsal root ganglion (DRG) neurons." (PMID 40151454, 2025). "Previous researches are in line with our results, and TLR4/IRAK1/TRAF6/NF-κB pathway was markedly activated under hyperglycemia." (PMID 36148071, 2022). "Compared to sustained hyperglycemia, glycemic fluctuation led to further increase in IL-1β, TNFα, RANKL, TLR2/4, IRAK1, and TRAF6 mRNA expression in peri-implant gingival tissues." (PMID 34401982, 2021).
intervertebral disc degeneration (4 papers, 2017 to 2022). "This resulted in intervertebral disc degeneration by disrupting the TNF receptor associated factor 6 (TRAF6)/NF-κB pathway." (PMID 33986262, 2021). "Our study was consistent with a previous report that HCG18 promotes intervertebral disc degeneration by sponging miR-146a-5p and regulating TRAF6 expression." (PMID 35240920, 2022).
liver fibrosis (4 papers, 2021 to 2023). "This action on TAB2, which recognizes K63-linked ubiquitin chains of RIP1 in TNF-α signaling or TRAF6 in IL-1β signaling, consequently inhibits the TAK1-MAPK cascade, a pathway critical in liver fibrosis progression." (PMID 37867509, 2023). "They found that depletion of TRAF6 attenuated liver fibrosis in diet-induced NASH models, supporting a role for TRAF6 in promoting liver fibrosis." (PMID 35668944, 2022). "TRAF6 overexpression in hepatocytes promotes ubiquitination-dependent activation of ASK1, contributing to the pathogenesis of hepatic fibrosis during the progression of nonalcoholic steatohepatitis (NASH)." (PMID 35668944, 2022). "TRIM38 directly binds to TAB2, and recognizes the K63 of RIP1 in the TNF-α signaling pathway through TAB2 to connect the ubiquitin chain or TRAF6 in the IL-1β signaling pathway, thereby inhibiting the key pathway TAK1-MAPK cascade in the process of liver fibrosis." (PMID 37867509, 2023). "Erk2-/- mice displayed reduced level of liver fibrosis, decreased cell proliferation rate and aggravated immunosuppression in response to fibrosis-inducing diet, whereas liver-specific TRAF6 overexpression restored fibrosis in Traf6+/− mice, which normally showed compromised fibrosis." (PMID 34440687, 2021).
lymphoma (4 papers, 2007 to 2024). A malignant (clonal) proliferation of B- lymphocytes or T- lymphocytes which involves the lymph nodes, bone marrow and/or extranodal sites. "Here the authors describe a direct complex of the viral oncoprotein LMP1 with the cellular TRAF6 protein as a critical virus-host interface for lymphoma survival and validate this complex as a potential therapeutic target." (PMID 38195569, 2024). "More interestingly, we found that the inactivation of TRAF6 by CRISPR/Cas9 caused a massive negative effect on lymphoma survival, which was comparable to the effect of LMP1 targeting itself." (PMID 38195569, 2024). "The direct recruitment of TRAF6 to LMP1 is essential for NF-κB activation by CTAR2 and the survival of LMP1-driven lymphoma." (PMID 38195569, 2024). "In summary, we reveal the molecular mechanism of TRAF6 engagement by LMP1 for signalling and lymphoma development." (PMID 38195569, 2024). "SMO stabilizes and activates TRAF6, suggesting that the SMO/TRAF6 axis can contribute to doxorubicin resistance in lymphoma." (PMID 33935743, 2021). "However, a potential role of TRAF6 in LMP1-dependent lymphoma has not been demonstrated." (PMID 38195569, 2024).
ovarian tumor (4 papers, 2015 to 2025). "In addition, ovarian tumor domain-containing 6B protein diminishes TRAF6-mediated K63-linked polyubiquitination of IRF3 and IRF7 to suppress IFN production." (PMID 36172355, 2022).
pulmonary fibrosis (4 papers, 2021 to 2025). Chronic progressive interstitial lung disorder characterized by the replacement of the lung tissue by connective tissue, leading to progressive dyspnea, respiratory failure, or right heart failure. "We further detected the expression levels of TGF-β, TRAF6, and Beclin1 in the lung tissues of mice and fibroblasts to evaluate the mechanism by which Galunisertib affects silicotic pulmonary fibrosis." (PMID 41378210, 2025). "The levels of ST2, MyD88, and TRAF6 proteins in bleomycin-induced pulmonary fibrosis tissues were elevated." (PMID 35046838, 2021). "Furthermore, TRAF6 overexpression protected mice from BLM-induced lung fibrosis, with a decrease in the number of activated fibroblasts, also called myofibroblasts." (PMID 35668944, 2022). "Given that TRAF6 is an intracellular protein widely expressed in epithelial cells, endothelial cells, and macrophages, future studies are needed to investigate the expression and role of TRAF6 in those cells during pulmonary fibrosis." (PMID 35668944, 2022). "The potential mechanism for protective of Galunisertib in silicosis-related pulmonary fibrosis may be attributed to the inhibition of the TGF-β/TRAF6/Beclin1 signaling pathway, which correlates with ameliorating autophagic flux—evidenced by reduced LC3II/I and p62 accumulation." (PMID 41378210, 2025). "However, the role of TRAF6 in lung fibrosis remains unknown." (PMID 35668944, 2022).
allergic rhinitis (3 papers, 2022 to 2025). Inflammation of the nasal mucous membranes caused by an IgE-mediated response to external allergens. "Similarly to previously, in the allergic rhinitis model (AR) and in β-lactoglobulin-induced food allergy, miRNA-146a showed anti-inflammatory potential by inhibiting the TLR4/TRAF6/NF-κB pathway." (PMID 41294623, 2025).
atrial fibrillation (3 papers, 2017 to 2023). A disorder characterized by an electrocardiographic finding of a supraventricular arrhythmia characterized by the replacement of consistent P waves by rapid oscillations or fibrillatory waves that vary in size, shape and timing and are accompanied by an irregular ventricular response. "TLR4/IRAK1/TRAF6/NF-κB, collagen I proteins expressions and incidence of atrial fibrillation (27.3%) were increased in DM group." (PMID 36148071, 2022). "SGLT-2i dapagliflozin may prevent diabetic rats' atrial remodeling and reduce the inducibility of atrial fibrillation partly by targeting TLR4/IRAK1/TRAF6/NF-κB inflammatory pathway." (PMID 36148071, 2022). "Finally, in order to reveal the possible mechanism, we verified the role of TLR4/IRAK1/TRAF6/NF-κB in the inhibition of atrial remodeling and atrial fibrillation by DAPA." (PMID 36148071, 2022).
autoimmune hepatitis (3 papers, 2018 to 2024). Hepatitis caused by autoantibodies. "The present study indicated that L-THP attenuated acute liver injury in ConA-induced autoimmune hepatitis by inhibiting apoptosis and autophagy via the TRAF6/JNK pathway." (PMID 30622431, 2018). "In addition, the conditional deletion of TRAF6 expression in murine thymic epithelial cells (TRAF6-ΔTEC mice) results in autoimmune hepatitis (AIH)." (PMID 33294443, 2020).
C. perfringens infection (3 papers, 2019 to 2023). "A previous study reported that the ileal TRAF6, NF-κB, and MyD88 expressions were up-regulated in piglets exposed to Clostridium perfringens infection, suggesting that the MyD88/NF-κB signaling pathway is closely related to host immune response induced by infection." (PMID 36865532, 2023).
chronic liver failure (3 papers, 2020 to 2022). Liver failure that develops slowly and gradually for some time, possibly for years, often as the result of cirrhosis, or malnutrition. "The autoubiquitination of TRAF6 can be inhibited by NEAT1, and an elevated TRAF6 level alleviates acute-on-chronic liver failure." (PMID 36011001, 2022). "In acute-on chronic liver failure, overexpression of NEAT1 decreased the ubiquitination level of TRAF6 and inflammatory response." (PMID 34837887, 2021).
Cirrhosis (3 papers, 2016 to 2019). A chronic disorder of the liver in which liver tissue becomes scarred and is partially replaced by regenerative nodules and fibrotic tissue resulting in loss of liver function. "In this large association study on Caucasian patients with decompensated cirrhosis we demonstrate for the first time an association of genetic germ line haplotype of the TRAF6 gene with the inflammatory status in peritoneal macrophages and with the risk of developing SBP." (PMID 28687809, 2017). "Second, our study provides evidence for a role of TRAF6 in mediating SBP as a severe complication of decompensated cirrhosis." (PMID 28687809, 2017). "Positive TRAF6 expression rates were 12.1, 21.6, 36.3, 49.7 % in the normal, cirrhosis, para-cancer and HCC tissues, respectively." (PMID 27708550, 2016). "Therefore, the risk to develop cirrhosis per se was not significantly influenced by the evaluated TRAF6 haplotype." (PMID 28687809, 2017). "In summary, our study revealed that the level of TRAF6 was higher in the HCC tissues compared to normal, cirrhosis and para-cancer liver tissues." (PMID 27708550, 2016). "The positive expression rate of TRAF6 protein was 49.7 % (85/171) in HCC tissues, significantly higher than para-carcinoma liver tissues (36.3 %, P = 0.012), cirrhosis tissues (21.6 %, P = 0.002), and normal liver tissues (12.1 %, P < 0.001)." (PMID 27708550, 2016). "Furthermore, TLR4 overexpression induced by DEN was decreased by Baishouwu extract, leading to the markedly down-regulated levels of MyD88, TRAF6, NF-κB p65, TGF-β1 and α-SMA in hepatitis, cirrhosis, and hepatocarcinoma." (PMID 31068809, 2019). "In the present work, the antinflammatory capability of Baishouwu extract mainly resulted in decreased levels of MyD88, TRAF6, NF-κB, IL-6 and TNF-α via the reduction of TLR4 expression in hepatitis, cirrhosis, and hepatocarcinoma stages of the HCC models induced by DEN." (PMID 31068809, 2019). "The positive expression rate of TRAF6 protein was 49.7 % in HCC, significantly higher than that of normal liver (12.1 %), cirrhosis (21.6 %) and adjacent non-cancerous tissues (36.3 %, all P < 0.05)." (PMID 27708550, 2016).
Cognitive impairment (3 papers, 2020 to 2023). Abnormal cognition is characterized by deficits in thinking, reasoning, or remembering. "It was found that treatment with a miR-146a agomir inhibits TRAF6 expression and reduced the cognitive impairment in AD mice." (PMID 36780558, 2023).
coronary heart disease (3 papers, 2010 to 2024). "Therefore, we measured TRAF6 mRNA in blood of a total of 325 patients undergoing coronary angiography categorized into three groups: no coronary heart disease (No CHD, N = 77), stable coronary heart disease (CHD, N = 178), and acute coronary syndrome (ACS, N = 70)." (PMID 20644648, 2010).
diffuse large B-cell lymphoma (3 papers, 2014 to 2022). "SMO stabilizes TRAF6 via recruiting USP8 to remove its K48 ubiquitination, which is associated with enhancement of TRAF6 K63 ubiquitination, thereby regulating AKT activation and cause doxorubicin resistance in diffuse large B cell lymphoma." (PMID 36202787, 2022). "Rigosertib, a multikinase inhibitor, has selective cytotoxicity to diffuse large B cell lymphoma, which is related to its ability to reduce the expression of unmodified and sulfonated TRAF6 and inhibit the nuclear entry of TRAF6." (PMID 33294443, 2020). "We report here that MYD88L265P signaling is constitutively active in both WM and diffuse large B-cell lymphoma cells leading to heightened MYD88L265P, IRAK and TRAF6 oligomerization and NF-κB activation." (PMID 24531446, 2014).
E. coli infection (3 papers, 2020 to 2023). "We also measured the expression of IRAK1 and TRAF6 along with the E. coli infection and found that they were decreased in U251 cells upon infection." (PMID 33985523, 2021). "Since miR-146a was experimentally proven to be associated with meningitic E. coli infection, whether it also targeted IRAK1 and TRAF6 in astrocytes needed further investigation." (PMID 33985523, 2021). "Moreover, miR-146a was determined to regulate the expression of IRAK1 and TRAF6 during E. coli infection." (PMID 33985523, 2021). "In this study on E.coli induction of GMECs, TLR4, TRAF3 and TRAF6 are significantly overexpressed as compared to the non-induced cells and the PPI network also suggests the key role of TLR4 and TRAF6/3 in the E. coli infection." (PMID 36604713, 2023).
endothelial dysfunction (3 papers, 2021 to 2025). In vascular diseases, endothelial dysfunction is a systemic pathological state of the endothelium (the inner lining of blood vessels) and can be broadly defined as an imbalance between vasodilating and vasoconstricting substances produced by (or acting on) the endothelium. "TRAF6 inhibition also significantly improved the endothelial dysfunction caused by hypertension." (PMID 39899926, 2025). "Meanwhile, TRAF6 inhibitor treatment in hypertensive animals showed beneficial effects such as improved endothelial dysfunction, reduced oxidative stress in cardiovascular tissues, and reduced aortic immune cell infiltration." (PMID 39899926, 2025). "The TRAF6 inhibitor treatment normalized endothelial dysfunction and reduced blood pressure in hypertensive wild type animals." (PMID 39899926, 2025). "Of note, these biochemical changes were also mirrored by functional changes—TRAF6 inhibition partially normalized increased systolic blood pressure, endothelial dysfunction, and aortic ROS formation in hypertensive mice." (PMID 38554187, 2024). "It was recently reported that TRAF6 was able to mediate endothelial dysfunction induced by a high glucose level through NF-κB- and AP-1-dependent signaling." (PMID 34912223, 2021). "•TRAF6 inhibition normalized blood pressure and endothelial dysfunction." (PMID 39899926, 2025). "Also, aortic ROS formation was increased in diabetic mice, leading to endothelial dysfunction, all of which was improved, at least by trend, by TRAF6 inhibitor treatment." (PMID 38554187, 2024). "Previously, we established that TRAF6 inhibition partially prevented endothelial dysfunction, weight gain, increase in HbA1c values, oxidative burst of whole blood leukocytes, cardiac RAGE signaling, vascular ROS formation, and impaired catalase/glutathione peroxidase 1 expression in db/db mice." (PMID 38554187, 2024).
endotoxemia (3 papers, 2012 to 2021). "Activation of the TLR4/TRAF6/NF-κB pathways was involved in the occurrence and development of intestinal mucosal injury and endotoxemia in mice with OJ." (PMID 31671112, 2019). "In conclusion, the TLR4 in the terminal ileum of mice with OJ was highly expressed and activated, and massive release of inflammatory factors was induced through the TLR4/TRAF6/NF-κB signaling pathways, which was involved in intestinal mucosal injury and endotoxemia." (PMID 31671112, 2019).
epilepsy (3 papers, 2015 to 2022). A brain disorder characterized by episodes of abnormally increased neuronal discharge resulting in transient episodes of sensory or motor neurological dysfunction, or psychic dysfunction. "The present study provided evidence that the TLR4/TRAF6/NF-κB signaling pathway is positively associated with neuroinflammation and apoptosis in pilocarpine-induced epilepsy." (PMID 35647304, 2022). "Within the network, many genes are related to inflammation and apoptosis, such as MAPK1, ATM, MYD88, RBL1, TRAF6, PIK3CD, IFNAR2, etc, indicating that these miRNAs may play a role in drug-resistant epilepsy through inflammation and apoptosis." (PMID 25984652, 2015).
esophageal cancer (3 papers, 2017 to 2023). A primary or metastatic malignant neoplasm involving the esophagus. "TRAF6 overexpression is also identified as a prognostic factor for breast and esophageal cancers." (PMID 30294322, 2018).
fungal infection (3 papers, 2013 to 2023). "OTUD1 regulated the production of antiviral cytokines and inflammatory cytokines by MAVS/TRAF3/TRAF6 signaling or NF-κB signaling cascades during viral and fungal infections." (PMID 38012669, 2023). "Using macrophages derived from TRAF6−/− mice, it has been shown that TRAF6 is required for NF-κB and JNK activation, and expression of proinflammatory cytokines in response to engagement of C-type lectin receptors during fungal infection." (PMID 23758787, 2013).
gouty arthritis (3 papers, 2018 to 2023). "Previous studies have demonstrated that miR-146a-deficient mice develop severe gouty arthritis via TRAF6, IRAK1 and NALP3 (NACHT, LRR and PYD domain-containing protein 3)-induced inflammasome dysregulation." (PMID 32863945, 2020). "Activation of NFATc1, c-JUN, and TNF receptor-associated factor-6 (TRAF6) downstream of the RANK-RANKL signal pathway has also been regarded as a crucial step for formation in osteoclast-like cells in the pathogenic mechanism of gout." (PMID 36986544, 2023).
gram-negative bacterial infections (3 papers, 2011 to 2020). Infections caused by bacteria that show up as pink (negative) when treated by the gram-staining method. "We show Gram-negative bacterial infection upregulates Siglec-E expression via the TLR4/MyD88/JNK/NF-κB/AP-1 signaling pathway, whereas infection with Gram-positive bacteria downregulates Siglec-E expression via the TLR2/RANKL/TRAF6/Syk signaling pathway." (PMID 32889432, 2020). "Since S. flexneri and S. typhimurium are both gram-negative, these results suggested that TIFA/TRAF6-dependent IL-8 expression was specifically triggered during gram-negative bacterial infections." (PMID 28222186, 2017).
head and neck cancer (3 papers, 2016 to 2021). A primary or metastatic malignant neoplasm affecting the head and neck. "To investigate the relationships between EMT, CSCs and TRAF6 in head and neck cancer, we discovered that the expression of TRAF6 in SCCHN was significantly correlated with EMT markers (i.e. Vimentin and Slug) and CSC markers (i.e. CD44, KLF4, ALDH1 and SOX2)." (PMID 29193723, 2018). "In summary, our results demonstrate that TRAF6 plays a functional role in the EMT phenotypes and in the CSC generation and maintenance in head and neck cancer cells." (PMID 29193723, 2018). "Therefore, inhibition of TRAF6 may be an effective approach to eliminate CSCs, reversing the EMT phenotype and consequently eradicating cancer cells to improve the prognosis of patients with head and neck cancer." (PMID 29193723, 2018).